APLN (apelin)
Diseases named in the same sentence as APLN in open-access papers (continued):
Sharing a sentence is not in itself a finding about the gene and the disease.
cancer (continued). "APLN regulates the microvasculature proliferation and APLN antagonists (F13A and bevacizumab) showed the cancer progression inhibition via reducing this vascular density." (PMID 38213742, 2024). "By participating in the formation of metastases, apelin is involved in the development and advanced stage of many cancers, especially breast, ovarian, RCC and gliomas." (PMID 37686525, 2023). "In recent years, there has been an increasing amount of data indicating a potential role for the apelin/APJ system in many cancers." (PMID 37190027, 2023). "The Apelin/APLNR system is increased in some cancers, is involved in tumor microenvironment reshaping and modulates tumor immune response." (PMID 37684649, 2023). "In a group of patients with diverse cancers, including lung cancer, gastrointestinal, breast, ovarian, uterus, and prostate cancers, apelin was proposed as a strong biomarker of cancer progression." (PMID 37048738, 2023). "In the present study, to clarify the effect of apelin in cancer cells, we used APJ-KO mice as a host in subcutaneous tumor cell inoculation models." (PMID 36776217, 2023). "When cell proliferation was compared in mock-transfected B16 cells and those transfected with apelin, we found that apelin significantly promoted the proliferation of apelin-overexpressing B16 cancer cells (p < 0.05)." (PMID 36776217, 2023). "Similar results have been reported in serum of patients with a significant increase in APLN levels, which is also related to the poor prognosis of cancer." (PMID 36614283, 2023). "Hypoxia caused by the hypermorphosis of tumor cells was shown to promote apelin expression via increased ROS-dependent hypoxia inducible factors (HIFs) activation, even in cancer stem cells." (PMID 36902176, 2023). "To analyze the effect of apelin on APJ in cancer cells, we overexpressed apelin in B16 cells (B16/apelin; p < 0.01)." (PMID 36776217, 2023). "It is now known that the apelin/APJ system is involved in the development of many cancers, particularly ovarian, breast, lung, liver, prostate, and glioma." (PMID 37190027, 2023). "We propose that apelin-APJ system in cancer cells induces tumor growth but negatively regulates EMT and tumor malignancy." (PMID 36776217, 2023). "Apelin also promotes cancer progression via enhanced cancer cell proliferation, migration, invasion and angiogenesis." (PMID 37298551, 2023). "Our integrated analysis suggests that the downregulation of DNMT3A influences Sertoli cell proliferation, likely through the modulation of the Apelin signaling pathway and MicroRNAs in cancer." (PMID 38264208, 2023). "Two significant pathways (Apelin signaling pathway and MicroRNAs in cancer) were identified by KEGG analysis." (PMID 38264208, 2023). "This review examined current evidence as to the relevance of blood-based measures of apelin to cancer." (PMID 36230579, 2022). "Several studies included in this review compared serum apelin concentration between patients with cancer and healthy controls or among different cancer types." (PMID 36230579, 2022). "Future research warrants more studies to advance in standardized measurement methods, produce a body of evidence based on the cancer types, and define the optimal cutoff points of apelin for accurate and early detection of cancer for personalized treatment." (PMID 36230579, 2022). "For use in clinical settings, serum apelin shows promise in furthering attempts to improve screening practices and provide individualized care for patients diagnosed with cancer." (PMID 36230579, 2022). "Serum apelin concentration is likely to vary based on the differing metabolic and physiologic processes among patients with different cancer types." (PMID 36230579, 2022). "Further research is needed to evaluate the utility of serum apelin as a prognostic marker for cancer progression." (PMID 36230579, 2022).
cancer (continued). "Nevertheless, apelin mainly shows anti-apoptotic activity, which is an introduction to research and a potential therapeutic target for various cancers but also for many dysfunctions and diseases of the neurological, cardiovascular, and urinary systems." (PMID 36611944, 2022). "Four studies analyzed ROC curves to find the optimal cutoff point of serum or plasma apelin in order to diagnose or monitor for disease progression of cancer patients." (PMID 36230579, 2022). "The ability of apelin to protect myotubes from atrophy in vitro, but its failure to do so in vivo, prompted us to further explore the mechanism of apelin resistance during cancer cachexia in vivo." (PMID 35406586, 2022). "Studies examined associations between apelin and various characteristics, showing potential uses for apelin as a biomarker in cancer." (PMID 36230579, 2022). "All 16 studies looked at differences in apelin between cases and controls or different classifications of cancer types." (PMID 36230579, 2022). "Most studies showed that apelin was higher in patients with cancer than in controls, while some showed lower apelin levels in cancer patients than controls." (PMID 36230579, 2022). "The KEGG pathway analysis disclosed viral carcinogenesis, apelin signaling, arginine and proline metabolism, transcriptional misregulation in cancer, Notch signaling, and cGMP-PKG signaling." (PMID 35359455, 2022). "Variations in results suggest that the relationship between circulating apelin and cancer differs among cancer types." (PMID 36230579, 2022). "Four studies of ROC analysis showed vastly different optimal cutoff points of serum apelin concentration to differentiate patients with cancer from controls, ranging from 0.160 ng/mL to 6.85 ng/mL." (PMID 36230579, 2022). "Apelin induces an upregulation of β-catenin and the oncogenes c-myc and cyclin D1, as well as glycolysis-related gene expression, and promotes cancer cell proliferation and migration." (PMID 36142542, 2022). "In various cancers, Apelin expression increases, and the Apelin/APLNR axis play an essential role in tumor development by enhancing angiogenesis, metastasis, cell proliferation, and cancer stem cell development and drug resistance." (PMID 35174205, 2022). "As expected, apelin stimulation promoted cancer cell proliferation when compared to untreated control cells." (PMID 36142542, 2022). "Using a cancer profiling array, a comparative analysis of apelin gene expression in normal and tumor tissues revealed an overall upregulation of apelin genes in one-third of human tumors." (PMID 36142542, 2022). "Research in the past decade has shown promise for apelin as a biomarker in cancer to predict treatment response and prognosis and detect cancer." (PMID 36230579, 2022). "Despite a vast body of evidence examining apelin expression in the tissue, studies on circulating apelin in blood for cancer are scarce and have shown considerable variations in methodology, making it difficult to draw definitive conclusions." (PMID 36230579, 2022). "Although results were inconsistent, most studies showed serum apelin increased in cancer compared to controls." (PMID 36230579, 2022). "Apelin expression is enhanced in various cancers, and the apelin/APJ axis has a crucial impact in tumor progress by reinforcing angiogenesis, metastasis, cell proliferation, and CSC plasticity and drug resistance." (PMID 35701840, 2022). "Angiogenic, lymphangiogenic and lymph node metastasis properties of the apelin secreted by cancer cells to promote tumor growth and metastasis is now well established." (PMID 36142542, 2022). "Inclusion criteria: measured circulating apelin in adults 18 years or older with cancer, and observational, cross-sectional, longitudinal, case–control, cohort, quasi-experimental, or randomized control trials." (PMID 36230579, 2022).
cancer (continued). "The second technique showed an upregulation of apelin expression in RCC compared to adjacent non-cancer tissue using the TCGA online database." (PMID 36553076, 2022). "To select the cachectic cell line more resistant to apelin for in vivo experiments, we treated the cancer cell lines able to cause cachexia (C26, LLC, MCG101) with these long-lived apelin peptides at increasing doses and times." (PMID 35406586, 2022). "More research is needed to investigate the role of serum apelin in cancer development, progression, and predictive value." (PMID 36230579, 2022). "Collectively, the APLN-APJ axis was proposed to be a druggable target in the cancer-stroma interplay in KIRC." (PMID 35079698, 2021). "There were 13 enrichment pathways, such as vascular smooth muscle contraction, cGMP-PKG signaling pathway, calcium signaling pathway, focal adhesion, ECM-receptor interaction, proteoglycans in cancer, apelin signaling pathway." (PMID 35141152, 2021). "In this review, we would summarize the newest progression on the role of apelin/APJ system as well as Apela signaling in different cancers." (PMID 33912466, 2021). "The role of apelin/APJ signaling in contributing to angiogenesis is also well-recognized in various cancers." (PMID 33912466, 2021). "Expression of apelin/APJ signaling occurred in many cancers, suggesting a potential role of this axis in cancer development and progression." (PMID 33912466, 2021). "The aim of the study was to establish the correlation between the level of the adipokines—adiponectin, resistin, apelin—and cancer cachexia." (PMID 32660156, 2020). "Although informative, these experiments remain descriptive and artificial because they are focusing only on apelin expression in cancer cells." (PMID 32681609, 2020). "KEGG enrichment analysis showed that RP11-89K21.1 targeted genes were significantly enriched in pathways in cancer, endocrine resistance and microRNAs in cancer, regulated apelin signaling pathway, Th17 cell differentiation and hippo signaling pathway." (PMID 32587476, 2020). "Pathway analysis identified apelin signalling pathway, regulation of actin cytoskeleton, transcriptional mis-regulation in cancer, oxytocin signalling and metabolic pathways as being significantly enriched pathways in these regions." (PMID 30819108, 2019). "In cancer, the APLN-APLNR signaling has been reported to promote maturation of tumor vasculature 15-17." (PMID 31410213, 2019). "Apelin was found to play an important role to promote tumor neoangiogenesis and sustain tumor expansion and progression in various human cancers." (PMID 30984306, 2019). "Consistent with our data, TCGA pan-cancer analysis revealed that APLN mRNA is most profoundly up-regulated in HCC among all cancer types." (PMID 31410213, 2019). "Having shown that inhibition of Apelin and administration of sunitinib markedly improves the outcome in different cancer models, we first assessed the impact of this combination therapy on the tumor vasculature." (PMID 31267692, 2019). "Various apelin peptides can stimulate tumor growth and proliferation of many types of cancer cells, including PCa." (PMID 31608109, 2019). "Evaluation of cancer progression based on comparison of clinicopathological parameters and apelin serum levels showed a relationship between stage of cancer and apelin concentration." (PMID 31547096, 2019). "The clinical implementation is facilitated by the fact that circulating Apelin levels serve as a biomarker for the cancer's sensitivity to anti‐angiogenic treatment." (PMID 31318171, 2019). "In cancer, apelin and its receptor (APJ) are involved in signalling pathways connected with migration and invasion leading to tumour growth and metastasis." (PMID 31547096, 2019).
cancer (continued). "It has recently emerged that apelin has pro-tumorigenic effects in various cancer models possibly by promoting angiogenesis and that inhibition of the apelin pathway was protective against tumour growth." (PMID 31882594, 2019). "Although these observations make the Apelin/Apelin receptor pathway a potentially attractive target for anti‐angiogenic cancer therapy, the detailed effects of its targeting for cancer treatment in vivo are poorly understood." (PMID 31267692, 2019). "Together, these results show that tumor cell‐derived as well as microenvironment‐derived Apelin contributes to cancer progression through stimulation of tumor angiogenesis, enhancing vessel leakiness and tumor hypoxia, and altered infiltration of immune cells." (PMID 31267692, 2019). "The vasculature in Apelin‐targeted cancer showed normalized features including improved perfusion and reduced leakage." (PMID 31318171, 2019). "We showed that the effect of four different apelin peptides increased the ability of cancer cells to migrate and invade examined cells trough influencing migratory protrusions formation and actin cytoskeleton rearrangement." (PMID 30127323, 2018). "Apelin fragments also decreased caspase-3 activity and poly-ADP ribose polymerase protein proteolysis, suggesting that apelin is involved in resisting cell death during cancer progression." (PMID 29875677, 2018). "Apelin is another adipokine whose levels are increased not only with obesity but also in several cancers." (PMID 29188139, 2017). "The top 5 upregulated miRNAs were mainly enriched in pathways in cancer and axon guidance, and the top 5 downregulated miRNAs were mainly enriched in pathways in cancer and apelin signaling pathway." (PMID 28904974, 2017). "Recent studies have also reported that the apelin/APJ system participates in many kinds of cancer including lung, gastroesophageal, colonic, prostate and endometrial cancer." (PMID 28484393, 2017). "In our in vitro study, we observed that all GC cell lines, including SGC-7901, MKN-45 and AGS had a 1.5 to 2 folds higher expression levels of Apelin compared to non-cancer cell line GES-1." (PMID 27733135, 2016). "Most recently, circulating apelin levels were reported to be significantly increased in cancer patients (vs. healthy controls) and, moreover, to correlate with disease stage and prognosis." (PMID 24962866, 2014). "Accordingly, apelin has been shown to stimulate blood vascular EC growth in various in vitro and in vivo angiogenesis systems, including a mouse model of cancer." (PMID 24962866, 2014). "Alteration of apelin cleavage sites generates apelin-dm peptide that effectively represses the malignant and metastatic phenotype of cancer cells and angiogenesis through modulation of apelin receptor dynamics, affinity, internalization, and diverse apelin signaling pathways." (PMID 39962271, 2025). "Apelin is related to ovarian, renal, and breast carcinogenesis and cancer progression." (PMID 40227577, 2025). "Through a series of in vitro and in vivo models simulating tumor progression and colorectal liver metastasis via intrasplenic injection of colon CT-26 and MC-38 cancer cells expressing apelin-dm, we unearthed compelling evidence of the anti-cancer and anti-angiogenic properties of apelin-dm." (PMID 39962271, 2025). "Additionally, apelin has been shown to have potent proangiogenic properties, inducing vessel formation and having detrimental effects in patients with cancer by facilitating tumor progression and metastatic processes." (PMID 41515992, 2025). "Hypoxia is a common feature of the microenvironment in almost all solid tumors and is frequently associated with angiogenesis and cancer growth, including CRC and has been reported to induce APLN expression in endothelial cells and Furin during regenerative angiogenesis." (PMID 39962271, 2025).
cancer (continued). "Moreover, apelin exerts influence on lipid uptake into cancer cells and accelerates fatty acid oxidation, which provides energy for cancer cells." (PMID 40076482, 2025). "Apelin impacts cancer cell migration and acts as a mitogenic factor." (PMID 40076482, 2025). "Elabela shares functional roles with apelin in angiogenesis and cancer." (PMID 39962271, 2025). "Further analysis revealed that the most significantly dysregulated proteins in response to APLN and APLN-DM expression in cancer cells were related to extracellular matrix regulation, metabolic activity, cytokine production, cell death, and growth (Dataset EV1)." (PMID 39962271, 2025). "Collagen adhesion is a complicated mechanism occurring during cancer invasion and metastasis, which may be the potential function of APLN+ endothelial cells." (PMID 39741182, 2025). "In summary, although the function of apelin in cancer is complex, it may serve as a potential therapeutic target." (PMID 38238841, 2024). "Pan‐cancer analysis of single genes also suggested that apelin may inhibit immune effector cells across various tumour types, highlighting its importance as a potential target for tumour angiogenesis." (PMID 39434201, 2024). "Inhibiting the release of Apelin peptide by cancer cells leads to an increase in pro-inflammatory responses in co-cultured macrophages, resulting in a significant upregulation of genes like IL-1β, IL-6, and TNF-α, along with a marked reduction in anti-inflammatory cytokine levels." (PMID 38650924, 2024). "Moreover, we found that Egr1 can effectively inhibit the occurrence of cancer by mediating Apelin and AGE–RAGE." (PMID 38647922, 2024). "Since the Apelin pathway is related to inositol metabolism, the pathways in cancer and senescence through central genes, the relationships between these pathways may maintain the hematopoietic stem cells in the G0 phase." (PMID 38881758, 2024). "The apelinergic system, specifically apelin and its receptor, together, has shown properties that could potentially protect the heart and mitigate the damages caused by DOX anti-cancer treatment." (PMID 38990214, 2024). "The role of apelin/APJ signaling in angiogenesis is also well recognized in different cancers." (PMID 36902176, 2023). "Most interestingly, PD-1, PD-L1 cancer immunotherapy pathways, antioxidant action of vitamin C, RhoGDI signalling, Apelin cardiac fibroblast signalling pathway and LXR/RXR activation pathways were downregulated significantly in older TG (> 12 M) compared with 3 M TG rats." (PMID 37403161, 2023). "However, there is evidence for the implication of other adipokines such as resistin, visfatin, apelin and chemerin in the development of cancer." (PMID 37686525, 2023). "APLN contributes to pathological processes, including obesity, heart attacks, diabetes, and cancer." (PMID 36632453, 2023). "APLN has been recognized for its emerging role as a cancer treatment target." (PMID 36614283, 2023). "Previously, studies have shown that inhibition of the APLN axis may have a therapeutic benefit in cancers." (PMID 36614283, 2023). "Apelin favors the proliferation and progression of various cancers." (PMID 37048738, 2023). "APLN, an adipokine secreted from adipose tissue, plays critical roles in many human cancers." (PMID 36632453, 2023). "“The “FoxO signaling pathway,” the “Apelin signaling pathway,” “Adherens junction,“ “Thyroid hormone signaling system,“ “Pathways in cancer, “ etc. were the key signaling pathways where the target genes of miRNAs that changed between days 15 and 18 of gestation were expressed." (PMID 36769111, 2023). "Next, to evaluate whether or not cell proliferation by apelin reflects in vivo tumor growth, we transplanted cancer cells into APJ-KO mice to eliminate the effect of apelin on cells other than cancer cells, especially ECs." (PMID 36776217, 2023).